IL12RB1 (interleukin 12 receptor subunit beta 1)
Diseases named in the same sentence as IL12RB1 in open-access papers (continued):
Sharing a sentence is not in itself a finding about the gene and the disease.
infection (32 papers, 2008 to 2025). The state of being infected such as from the introduction of a foreign agent such as serum, vaccine, antigenic substance or organism. "In this work, we analyze the transcriptional landscape associated with adaptation in an emerging zoonotic pathogen, Bordetella hinzii, as it evolved during a 45-month infection in an IL12Rβ1-deficient immunocompromised host." (PMID 40021638, 2025). "Invasive salmonellosis is the second most common infection seen in 38% of IL12Rβ1-deficient patients and 25% of IL12p40-deficient patients." (PMID 38535546, 2024). "IL12Rβ1 deficiency and the consequent reduced IL-12 responsivity result in impaired production of IFNγ by NK cells and T cells, which impairs control of infection by mycobacteria and other intracellular bacteria." (PMID 28804486, 2017). "Though in our experience, some IL12RB1-deficient patients can have recurrent infections." (PMID 38535546, 2024). "The second most common infection was Salmonellosis, affecting 40% of IL12Rβ1-deficient individuals." (PMID 28804486, 2017). "Among the genes positively regulated by IRF1 signalling and directly bound by IRF1, we found the already known targets, guanylate-binding protein 2 (Gbp2) and Gbp5 (refs 50, 51), which contribute to clearance of infection as well as Th1-associated genes, including Il12rb1 (refs 1, 36)." (PMID 28497800, 2017). "Moreover, in Brazilian patients with PCM, reports of polymorphisms on IL-4 and IL-12Rβ1 genes have shown the relevance of IL4-590 C/T and IL12RB1 641 A/G SNPs in association with infection or clinical forms, contributing to a better understanding of the immunopathogenesis of this disease." (PMID 33117339, 2020). "First, the BCG load and immune responses were not dynamically monitored, which made it impossible to compare the compacities of wild-type and Il12rb1−/− mice in controlling BCG infection at a time point either earlier or later than 4 weeks post infection." (PMID 35891311, 2022). "A few patients of IL-12Rβ1 had a recurrence of infections and worsening of symptoms despite being on treatment." (PMID 33732252, 2021). "IL-12Rβ1 deficiency, therefore, should probably be suspected in any patient with an unusual infection with intracellular pathogens even in the absence of parental consanguinity." (PMID 29256176, 2018). "Similarly, in TMEV-infection, microglia exclusively expressed Il12b and Il12rb1." (PMID 34311763, 2021). "Our results indicate that the expression of IL6, IL12B, IL1R2, IL23R, IL12RB1 and IL12RB2 increased after DTMUV infection." (PMID 35585616, 2022). "Almost 64% of patients had a single infection with MTBC, this finding is consistent with the finding reported previously in a survey of 141 IL-12Rβ1 patients." (PMID 33732252, 2021). "IL-12 signals through a receptor comprising IL-12Rβ1 and IL-12Rβ2 and is a potent inducer of IFN-γ which mediates both clearance of infection and immunopathology in infections with Plasmodium parasites." (PMID 29381699, 2018). "Furthermore, several additional transcripts associated with innate effector cell function were upregulated throughout acute infection, compared to pre-infection, including NKG7, KLRD1, EOMES, CD160, SLAMF5, and IL12RB1." (PMID 31937782, 2020). "In conclusion, the gene-expression signature predominant in livers of BALB/c mice 10 days after infection with L. infantum is characterized by the overrepresentation of IL12-mediated signaling events (FDR=0.003) with the strong upregulation of Il12rb2, Ifng, Nos2, Il12rb1, and Il12b." (PMID 34281214, 2021).
cancer (16 papers, 2019 to 2025). A tumor composed of atypical neoplastic, often pleomorphic cells that invade other tissues. "Hence, the IL-12RB1 gene appears interesting as a candidate gene for testing susceptibility to cancers." (PMID 35646062, 2022). "In particular, the IL-12 p40 monomer helped cancer cells escape cell death by suppressing IL12RB1 internalization; therefore, PCa cell apoptosis was induced after IL-12 p40 neutralization and consequent IL12RB1 internalization." (PMID 37108754, 2023). "We found that IL12RB1 gene promoter was significantly hypomethylated in cancer tissue (85.2%) in comparison to healthy oral mucosa (0%)." (PMID 37175405, 2023). "Moreover, we report, for the first time, the association of IL12RB1, CA11, CD276, and APBB1IP with cancer-associated inflammation." (PMID 37228491, 2023). "In a similar manner, ARG1 plays a pivotal role in tumorigenesis and metastasis, and it can be used as potential diagnosis biomarker for cancer progression, while the soluble form of IL12RB1 may truncate the capacity of the immune system to trigger a pro-inflammatory Th1/Th17 response." (PMID 40806007, 2025). "It is worth noting that IL12RB1, CD276, and APBB1IP are involved in cancer surveillance, inhibition of T-cell mediated responses, and T-cell recruitment, respectively, whereas CA11 may induce proliferation and invasion of gastrointestinal tumors." (PMID 37228491, 2023). "LILRB4 was highly correlated with IL12RB1 and IL2RB across the various cancer types." (PMID 33974041, 2021).
infectious disease (5 papers, 2008 to 2018). A disorder directly resulting from the presence and activity of a microbial, viral, or parasitic agent in humans. "Mandatory screening for IL-12Rβ1 mutations that cause a defective IL-12/IL-23/IFN-γ axis would not only improve the quality of patient care but also increase the safety monitoring for potential complications including infectious diseases in these subjects." (PMID 29256176, 2018). "Second, the clinical penetrance of mutations, in terms of infectious diseases can be low, as observed in MSMD for patients with complete IL-12Rβ1 deficiency, or even extremely low, as in patients with autosomal dominant IFN-γR2 deficiency." (PMID 23472171, 2013).
bacterial infections (1 paper, 2024). "Several bacterial infections induce p40HDs that bind IL-12Rb1 dimers on myeloid cells to stimulate chemokine production and enhance phagocytic function, but p40HDs have not been reported to impact naive or memory CD8+ T cell activation, including stimulation of proliferation." (PMID 38271093, 2024).
hematologic cancers (1 paper, 2023). "Moreover, in our IEI patient cohort defects in the IL12RB1 gene were exclusively presented with non-hematologic cancers and no individual with hematologic cancers was detected." (PMID 36765721, 2023).
neurological diseases (1 paper, 2019). "However, the relationship between Il12rb1, Lrp10, and NF-κB in inflammatory responses and neurological diseases remains unknown." (PMID 31636619, 2019).
IL12RB1 also shares sentences with these, for which no sentence is quoted: autoimmune disease (3 papers); coccidioidomycosis (3); influenza (3); anaemia (2); experimental autoimmune encephalomyelitis (2); genetic disorders (2); Mendelian susceptibility to mycobacterial diseases (2); pneumonia (2); acute myeloid leukemia (1); adenocarcinoma (1); adult onset immunodeficiency syndrome (1); allergic disease (1); aneurysm (1); ankylosing spondylitis (1); autoimmune cardiomyopathy (1); autoimmune hemolytic anemia (1); Behcet disease (1); bronchopneumonia (1); celiac disease (1); cervical cancer (1); Crohn disease (1); cutaneous leishmaniasis (1); cutaneous vasculitis (1); eosinophilia (1); esophageal cancer (1); gastric cancer (1); gastrointestinal tumors (1); glioblastoma (1); Graves ophthalmopathy (1); heart failure (1).
A further 31 diseases each share a sentence with IL12RB1 in 1 paper.